ELN (elastin)
Diseases named in the same sentence as ELN in open-access papers (continued):
Sharing a sentence is not in itself a finding about the gene and the disease.
ectopia lentis (2 papers, 2011 to 2021). "It is suggested that elevated Hcy concentrations modify sulfhydryl groups on proteins and interfere with the cross-linking of sulfhydryl groups in proteins such as elastin, which is considered to lead to the ectopia lentis and skeletal abnormalities." (PMID 33985475, 2021). "We speculate that the mutation may have deleterious effects on the anchorage function of ciliary zonule, but may not effect the conformation of fibrillin or elastin fiber and the affected patients appear isolated ectopia lentis without abnormalities in the cardiovascular and skeletal system." (PMID 22219643, 2011).
endocardial fibroelastosis (2 papers, 2015 to 2021). Endomyocardial fibroelastosis is a cause of unexplained childhood cardiac insufficiency. "Endocardial fibroelastosis (EFE), characterized by a diffuse endocardial thickening through collagen and elastin fibers, predominantly develops in immature left atrium (LA) and left ventricle (LV)." (PMID 26064914, 2015).
Granuloma (2 papers, 2025). A compact, organized collection of mature mononuclear phagocytes, which may be but is not necessarily accompanied by accessory features such as necrosis. "MMP12 is a macrophage elastase that degrades extracellular matrix fibres, in particular elastin, and that is involved with granuloma formation; MMP12 was one of the top five upregulated genes in typical GCA (available at Rheumatology online)." (PMID 39837478, 2025).
Hurler disease (2 papers, 2012 to 2023). "In elastoma and myxedema, tissue mass formation is observed due to the deposition of adipose tissue and mucopolysaccharides in regions of dermal elastin degradation similar to Hurler Disease." (PMID 37001705, 2023). "Interestingly in Hurler disease patients, heparan sulfate accumulation on elastic fibers also prevented degradation mediated by cathepsin V showing differential regulation of elastin degrading proteases." (PMID 37001705, 2023). "In Hurler disease mice, upregulation of cathepsin S and MMP-12 was responsible for the degradation of elastin and aortic dilation." (PMID 37001705, 2023).
Intellectual disability (2 papers, 2017 to 2024). "Furthermore, we identified one patient with a smaller 167.21-kb microdeletion within the WSCR, including EIF4H, LAT2, RFC2, and CLIP2, but not comprising the ELN gene and segregating in the family with non-syndromic intellectual disability." (PMID 39368701, 2024).
interstitial lung disease (2 papers, 2018 to 2024). A diverse group of lung diseases that affect the lung parenchyma. "We investigated possible factors involved in elastin degradation and evaluated whether a similar pattern of elastin degradation can be found in BALF samples of patients with interstitial lung diseases known to have aspirated." (PMID 30170599, 2018). "BALF samples from subjects without interstitial lung disease and negative pepsin) (lanes 1 to 6) show a single band in the 70 kDa range, without evidence of smaller molecular weight elastin-derived peptides." (PMID 30170599, 2018).
intracerebral hemorrhage (2 papers, 2017 to 2021). A cerebrovascular disorder characterized by bleeding into one or both cerebral hemispheres including the basal ganglia and the cerebral cortex. "Due to the abnormal elastin fibers in various organs, complications often occur, including cardiovascular abnormalities, gastrointestinal bleeding, epistaxis, and intracerebral hemorrhage." (PMID 28978321, 2017).
invasive carcinoma (2 papers, 2019 to 2023). A carcinoma that is not confined to the epithelium, and has spread to the surrounding stroma. "All paraffin blocks of invasive carcinoma from each patient were subjected to HE staining, elastin staining + CK (AE1/AE3) immunohistochemistry (E&IHC), and CD31/D2-40 + CK (AE1/AE3) double immunohistochemistry (D-IHC)." (PMID 37087442, 2023).
ischemia (2 papers, 2021 to 2022). A hypoperfusion of the BLOOD through an organ or tissue caused by a PATHOLOGIC CONSTRICTION or obstruction of its BLOOD VESSELS, or an absence of BLOOD CIRCULATION. "In addition, the TME contains higher levels of collagen, while arterial stiffening, which is common in PAD and ischemia, is a result of less elastin and more collagen." (PMID 35087885, 2021).
ischemic stroke (2 papers, 2019 to 2025). A stroke disorder caused by obstruction of blood flow to the brain, due to thrombotic (local blood clot formation) or embolic (due to a blood clot or other material traveling from another site) event. "The degradation of elastin by elastolytic enzymes is a hallmark of tissue ageing and of cardiovascular diseases such as atherosclerosis, ischemic stroke and peripheral artery disease." (PMID 30759294, 2019). "Mutation in the ELN gene was previously associated with ischemic stroke in adult patients." (PMID 40650005, 2025). "The degradation products of elastin, i.e. elastin-derived peptides (EDPs), are detectable in the cerebrospinal fluid of both healthy subjects and patients with ischemic stroke, which suggests their involvement in the nervous system’s ageing process." (PMID 30759294, 2019). "The products of elastin degradation, namely elastin-derived peptides (EDPs), are detectable in the cerebrospinal fluid of healthy individuals and in patients after ischemic stroke, and their number increases with age." (PMID 30759294, 2019).
Kawasaki disease (2 papers, 2013 to 2021). A rare inflammatory disease characterized by an acute febrile, systemic, self-limiting, medium-vessel vasculitis primarily affecting children. "This may be because acute inflammation in Kawasaki disease leads to the damage of elastin, and as a result weakens the blood vessels." (PMID 23650564, 2013).
leptospirosis (2 papers, 2010 to 2017). A contagious bacterial infection caused by spirochetes of the genus Leptospira. "Convalescent leptospirosis patient sera were also tested for effects on leptospiral binding to elastin, but the strong agglutinating effect prevented assessment of leptospiral adhesion." (PMID 20844573, 2010). "These elastin-rich tissues are highly relevant to leptospirosis as infection includes entry through skin abrasions or mucous membranes, dissemination through the circulation, and attachment to vascular, renal, pulmonary, uterine, and other tissues." (PMID 20844573, 2010). "In the severe form of leptospirosis, infected patients could present life-threatening pulmonary hemorrhage, which might be related to the ability of Leptospira binding to lung elastin." (PMID 28536676, 2017). "Further, we investigated whether convalescent leptospirosis patient sera enhance leptospiral binding to skin elastin." (PMID 20844573, 2010). "Further, the OmpL37 antiserum but neither leptospirosis patient sera nor Leptospira-infected hamster sera enhanced the binding of recombinant OmpL37 to immobilized skin elastin." (PMID 20844573, 2010). "We also investigated the effects of convalescent leptospirosis patient sera and Leptospira-infected hamster sera on recombinant OmpL37 binding to skin elastin but no statistically significant enhancement was observed." (PMID 20844573, 2010).
leukemia (2 papers, 2020 to 2023). A malignant (clonal) hematologic disorder, involving hematopoietic stem cells and characterized by the presence of primitive or atypical myeloid or lymphoid cells in the bone marrow and the blood. "The time dependent pattern of the first phase leukemia death incidence could correlate to the pattern of elastin expression with external exposure and the pattern of the solid cancers could correlate to that with the internal exposure, which is likely owing to severe damage in stem cells." (PMID 32586004, 2020).
melasma (2 papers, 2022 to 2023). "In skin fibroblasts, CDH11 regulates collagen and elastin synthesis, and its down-regulation can influence a decrease in dermal repair in melasma skin." (PMID 35840442, 2022).
mitral valve prolapse (2 papers, 2010 to 2024). A fairly common and often benign valvular heart disorder characterized by redundancy or hooding of mitral valve leaflets so that they prolapse into the left atrium, often causing mitral regurgitation. "The observed mitral valve prolapse in MFS patients and experimental mouse models has been correlated with elastin degradation similar to aging-related elastolysis, where elastin degradation has been well-established to contribute to normal skin and vascular aging." (PMID 38461168, 2024).
Morquio A disease (2 papers, 2012 to 2022). "Here we show that cathepsin S (CTSS) and elastin (ELN) can be used as biomarkers of extracellular matrix remodeling in Morquio A disease." (PMID 35620518, 2022).
myopia (2 papers, 2025). "Previous studies have indicated that LOXL3 encodes lysyl oxidase-like protein 3, which is responsible for the crosslinking of collagen and elastin, potentially affecting scleral stability and associating with non-syndromic early-onset high myopia." (PMID 41259386, 2025).
non-small cell lung carcinoma (2 papers, 2020 to 2021). A group of at least three distinct histological types of lung cancer, including non-small cell squamous cell carcinoma, adenocarcinoma, and large cell carcinoma. "ELN is also involved in the EMT of non-small cell lung cancer." (PMID 34359550, 2021). "ELN and collagen together may be associated with EMT in non-small cell lung cancer." (PMID 32171282, 2020).
ocular hypertension (2 papers, 2020 to 2022). Abnormally high intraocular pressure. "In the acute ocular hypertensive model, elastin took immediate reaction to resist the elevated IOP." (PMID 32719611, 2020).
pancreatic cancer (2 papers, 2022 to 2024). "ATG5-ATG7-NCOA4 pathway is critical for the regulation of iron metabolism and knockout of ATG7 can lead to a limited elastin-induced ferroptosis in pancreatic cancer cell lines." (PMID 35911966, 2022).
Polypoidal choroidal vasculopathy (2 papers, 2015 to 2022). The presence of aneurysmal 'polypoidal' lesions in the choroidal vasculature. "The expression of proteases in the RPE leads to degradation of elastin in the choroid mimicking features of polypoidal choroidal vasculopathy, a common subtype of neovascular AMD." (PMID 35884862, 2022).
pterygium (2 papers, 2021 to 2022). A wedge-shaped fibrovascular lesion arising from the bulbar conjunctiva and extending to the cornea. "The main histologic findings in pterygium’s specimens include squamous metaplasia, hyperplasia of goblet cells, underlying disrupted Bowman’s layer, stromal fibroblasts and vessels, altered extracellular matrix with accumulation of collagen and elastin fibers, and inflammatory infiltration." (PMID 34997134, 2022). "The fibrovascular tissue that makes up pterygium is characterized by an increase in elastin and myofibroblasts, which plays a critical role in the migration and growth of pterygium." (PMID 34945227, 2021). "These alterations may be an initial change in the development of pterygium at the level of the limbus in which the components of the stromal connective tissue, elastin, and tropoelastin (TE) are altered." (PMID 34945227, 2021).
Pulmonary artery stenosis (2 papers, 2021 to 2022). An abnormal narrowing or constriction of the pulmonary artery, in the main pulmonary artery and/or in the left or right pulmonary artery branches. "Their results indicate the importance of screening for the ELN gene in patients with vascular abnormalities, especially SVAS and pulmonary artery stenosis, and reinforce the view that haploinsufficiency at ELN is the primary cause of these vascular lesions." (PMID 34238994, 2021). "We propose that the decrease of ELN protein level may cause this pedigree vascular abnormality, especially pulmonary artery stenosis, and reinforce the view that ELN insufficiency is the primary cause of these vascular lesions." (PMID 34238994, 2021). "Our results indicate that ELN mutation may be involved in CHDs accompanied with pulmonary artery stenosis and should be screened in prospective clinical practice." (PMID 34238994, 2021). "A heterozygous mutation of the ELN gene (NM_001278939.1: c.1939G>T, p.Gly647Ter) was associated with a CHD with pulmonary artery stenosis pedigree through WES." (PMID 34238994, 2021). "The ELN heterozygous mutation (NM_001278939.1: c.1939G>T, p.Gly647Ter) was associated with the CHD accompanied with a pulmonary artery stenosis family." (PMID 34238994, 2021). "In the present study, the mutation site increased ELN protein level, which is not normally seen in this pedigree (pulmonary artery stenosis)." (PMID 34238994, 2021).
sarcopenia (2 papers, 2014 to 2023). Progressive decline in muscle mass due to aging which results in decreased functional capacity of muscles. "Decline in human muscle mass and strength (sarcopenia) is a hallmark of the aging process; whether methylation changes in genes such as LMNA, TNNT3, ELN and HDAC4 are a cause or consequence of this process merits investigation." (PMID 24112369, 2014).
scoliosis (2 papers, 2019 to 2024). A congenital or acquired spinal deformity characterized by lateral curvature of the spine. "Molecular studies of the human connective tissue extracellular matrix composition have established changes in the amount of collagen and elastin related to different degenerative diseases, such as scoliosis, spinal disc degeneration, and general connective tissue laxity." (PMID 38514709, 2024).
silicosis (2 papers, 2022 to 2025). Silicosis is a respiratory disease caused by breathing in (inhaling) silica dust. "The expression of ECM components (fibronectin, collagen I, elastin) also increased during silicosis progression." (PMID 39721015, 2025). "Van Gieson (VG) and elastin staining showed excessive collagen deposition in pulmonary mesenchyme in silicosis group." (PMID 35959439, 2022).
skin infection (2 papers, 2018 to 2021). An inflammatory process affecting the skin, caused by bacteria, viruses, parasites, or fungi. "Although the role of EbpS has not been implicated in S. aureus skin infections, by binding to elastin, EbpS may promote colonization of skin tissues that are rich in elastin." (PMID 34177874, 2021). "Application of CSP-4 to inflamed skin of hairless mice infected with drug-resistant S. aureus (DRSA) significantly reduced skin infections without damaging dermal collagen or elastin." (PMID 29643997, 2018).
stenosis (2 papers, 2024). "Consequently, genetic mutations in the ELN gene that reduce elastin protein levels are associated with focal arterial stenosis or narrowing of the arterial lumen." (PMID 39457566, 2024).
Striae distensae (2 papers, 2015 to 2024). Thinned, erythematous, depressed bands of atrophic skin. "Microneedling has been shown to be an effective treatment modality for striae distensae by increasing the production of elastin and collagen and enhancing epidermal thickness." (PMID 38439103, 2024).
Telangiectasia (2 papers, 2019 to 2025). Telangiectasias refer to small dilated blood vessels located near the surface of the skin or mucous membranes, measuring between 0.5 and 1 millimeter in diameter. "Collectively, the histological characteristics of photoaging can be summarised as follows: collagen and elastin degradation, inflammatory cell infiltration to the dermis, telangiectasia, and structural changes in the epidermis." (PMID 40290806, 2025). "The most notable features of skin by UV radiation are an inordinate deposition of abnormal elastin complex and the impairment of collagen fibers, which are accompanied by skin thickening, depigmentation, and telangiectasia; so, protection from UV light is important." (PMID 31126154, 2019).
thyroid cancer (2 papers, 2021 to 2025). "INSL3 was also demonstrated to promote early tumor cell invasiveness in human thyroid carcinoma cells by enhancing their metabolic activity and elastin-degrading potential via increasing the production of the lysosomal enzymes cathepsin-L and cathepsin-D." (PMID 34211824, 2021). "Studies have also examined elastin and RSL3, both of which have demonstrated potential to induce ferroptosis in thyroid cancer cell lines, offering new therapeutic avenues." (PMID 39917169, 2025).
Umbilical hernia (2 papers, 2013 to 2018). Protrusion of abdominal contents through a defect in the abdominal wall musculature around the umbilicus. "Diaphragmatic, inguinal, and umbilical hernia are all associated with connective tissue weakness, and previously extracellular matrix proteins such as collagens, fibronectin, elastin and matrix metalloproteinases have been suggested to be involved." (PMID 29843603, 2018). "A marked reduction in normal elastin and collagen deposits were also observed in connective tissues adjacent to the umbilical hernia." (PMID 23696835, 2013).
vascular malformation (2 papers, 2018 to 2019). A non-neoplastic disorder that is the result of defects of vascular morphogenesis. "Restoring sufficient quantity of elastin should then result in prevention or inhibition of vascular malformations and improvement in arterial blood pressure." (PMID 31138170, 2019). "In this study, we show that extracranial vascular malformations, like brain AVMs, are characterized by diminished and incomplete smooth muscle actin (αSMA) in the vascular smooth muscle cells (VSMC) of AVM, and diminished elastin coverage in the internal elastin lamina (IEL) of AVMs." (PMID 30573741, 2018).
vitamin A deficiency (2 papers, 2005 to 2024). Deficiency of vitamin A due to malnutrition, malabsorption, or dietary lack. "Vitamin A deficiency negatively impacts lung health by promoting elastin degradation and oxidative injury." (PMID 39371942, 2024). "There is also a decrease in elastin and the concentration of elastic fibers in vitamin A deficiency, which may reduce the ability of the parenchyma to resist deformation after CCh administration, resulting in a smaller CCh-mediated increase in the shear modulus than in vitamin A sufficient rats." (PMID 16033655, 2005).
acquired cutis laxa (1 paper, 2025). An instance of cutis laxa that is acquired during the lifetime of the individual. "Elastosis perforans serpiginosa (EPS) and acquired cutis laxa are rare elastin-related dermatoses associated with long-term penicillamine therapy." (PMID 41312328, 2025).
alcoholism (1 paper, 2022). "One hypothesis is that the subproducts of alcoholism interfere with cell–cell interactions during degradation of the elastin membrane." (PMID 35012210, 2022). "This study aimed to evaluate the use of collagen, elastin, or chitosan biomaterial for bone reconstruction in rats submitted or not to experimental alcoholism." (PMID 35012210, 2022). "The aim of the present study was to evaluate the use of collagen, elastin, or chitosan biomaterial for bone reconstruction in rats submitted or not to experimental alcoholism." (PMID 35012210, 2022). "Regarding the groups grafted with elastin, rats not exposed to alcoholism (G3) exhibited the highest volume of newly formed bone in this study (47.29 ± 0.97)." (PMID 35012210, 2022).
alpha 1-antitrypsin deficiency (1 paper, 2020). Alpha-1-antitrypsin deficiency is a hereditary disease that develops in adulthood and is characterized by chronic liver disorders (cirrhosis), respiratory disorders (emphysema), and rarely panniculitis. "The genetic disorder alpha 1 antitrypsin deficiency (AATD) results in reduced levels of alpha 1 antitrypsin (AAT) in the lung and an imbalance between AAT anti-protease activity and the activity of proteases that degrade elastin and connective tissues." (PMID 33304809, 2020).
angina (1 paper, 2021). "In patients with atypical angina, clinicians might consider routine examination of s-elastin and elastase for early and convenient detection of coronary dilatation." (PMID 33315345, 2021).